FOXM1 (forkhead box M1)
Diseases named in the same sentence as FOXM1 in open-access papers (continued):
Sharing a sentence is not in itself a finding about the gene and the disease.
lung cancer (continued). "These new insights may contribute to further investigations about the role of FOXM1 in therapeutic response of lung cancer." (PMID 36292640, 2022). "Based on these in silico data, we hypothesized that the CD274 promoter region of lung cancer cells is a potential target of the FOXM1 TF." (PMID 35975458, 2022). "Specifically, in lung cancer, FOXM1 has been found to be co-expressed with CENE and could regulate the expression of MMP2, contributing to LUAD growth and metastasis." (PMID 35036134, 2021). "Overall, these studies indicated that circRNAs promoting FOXM1 expression or derived from FOXM1 itself, could promote lung cancer progression, suggesting FOXM1 may function as a new molecular target for lung cancer treatment." (PMID 34295810, 2021). "Similarly, ALKBH5 contributes to lung cancer cell proliferation and metastasis following intermittent hypoxia by inducing the expression of FOXM1 protein in an m6A-dependent manner." (PMID 34491904, 2021). "Moreover, FOXM1 can act as a downstream target of many miRNAs in lung cancers, such as miR-149, miR-134, miR-509-5p, miR-361-5p and miR-145." (PMID 34301223, 2021). "FOXM1 stimulates cellular proliferation and its expression is induced in lung cancers." (PMID 32271749, 2020). "To test this hypothesis, we examined the effects of FAM188B knockdown on FOXM1 levels and its ubiquitination along with cell growth in lung cancer cell lines." (PMID 33142744, 2020). "Genetic deletion of Foxm1 in macrophages inhibited lung cancer." (PMID 32271749, 2020). "In addition to lung cancer, it was also shown that FOXM1 is highly expressed in several other chronic lung diseases, including COPD, asthma and IPF." (PMID 32271749, 2020). "A growing number of studies have focused on the relationship between abnormal FOXM1 expression and pulmonary diseases, such as lung cancer, chronic obstructive pulmonary disease (COPD), asthma, acute lung injury (ALI), pulmonary fibrosis, and pulmonary arterial hypertension (PAH)." (PMID 30992007, 2019). "FOXM1 correlates with poor outcome, and elucidation of its effect on proliferation, invasion, metastasis and replicative immortality provides new insight into understanding the mechanisms of lung cancer progression and drug resistance." (PMID 30992007, 2019). "Thereafter, we measured expression of five genes commonly considered as proliferative markers, Ki67, TOPO IIa, BUB1, CENP2, FOXM1, including in lung cancers; in the 10 NF-YA cohorts, all showed progressively decreasing levels from high-to-low NF-YA expressing tumors." (PMID 31744190, 2019). "Overall, FOXM1 mRNA expression in lung cancer is higher than that in normal tissues." (PMID 30992007, 2019). "However, another recent study also demonstrated that endothelial-specific expression of FOXM1 inhibits lung cancer growth by limiting lung inflammation and inhibiting canonical Wnt/β-catenin signaling in lung alveolar type II epithelial cells." (PMID 30992007, 2019). "However, targeting FOXM1 is an effective therapeutic strategy for the treatment of lung cancer and COPD in mice." (PMID 30992007, 2019). "As a tumor suppressor in lung cancer, miR-361-5p could directly target FOXM1 leading to down-regulation of FOXM1 expression in lung cancer cells." (PMID 31185898, 2019). "Furthermore, IPA upstream analysis predicted the activation or inhibition state of many important transcription factors that were previously reported to be involved in the pathogenesis of lung cancer such as FOXM1, NRF2, TP63, NKX2-1, and ATF3 18,36–39." (PMID 31444368, 2019). "Moreover, FOXM1 promotes metastasis by inducing EMT in lung cancer through activation of the AKT/p70S6K pathway, while inhibiting the PI3K/AKT pathway has the opposite effect." (PMID 30992007, 2019). "Increased expression of FOXM1 in response to high level of ROS may be one reason for lung cancer in SM-victims." (PMID 29552057, 2017).
lung cancer (continued). "We speculate that increased expression of FOXM1 and APOE genes is more likely linked to overproduction of ROS and OS in mustard lungs that may increase the risk of lung cancer among these patients." (PMID 29552057, 2017). "Macrophage-specific inactivation of Foxm1 reduced cancer-associated inflammation and decreased tumor growth in chemically-induced lung cancer models, indicating that Foxm1 expression in macrophages is important for regulation of cancer-associated inflammation during tumor promotion." (PMID 25254494, 2014). "Also, investigators found that constitutive expression of FOXM1 cooperated with activated Kras to induce lung cancer growth in vivo." (PMID 24325450, 2013). "Our data revealed that inhibition of FoxM1 could suppress the metastatic ability, while up-regulated expression level of FoxM1 in lung cancer cells enhanced the migratory and invasive properties in vitro and in vivo." (PMID 23536876, 2013). "The important role of Foxm1 in lung cancer has already been established." (PMID 19672312, 2009). "The present data demonstrates that Foxm1 expression in respiratory epithelial cells is required for progression/expansion of chemically-induced lung cancer in vivo and provides support for the concept that Foxm1 functions in a cell autonomous manner during pulmonary carcinogenesis." (PMID 19672312, 2009). "In addition, the FOXM1/Rad51 axis protect lung fibroblasts from radiation-induced cell death, indicating that this axis may be involved in lung cancer radiosensitivity." (PMID 38296976, 2024). "Hence, targeting FOXM1 using TST, a natural FOXM1 inhibitor that appears to abrogate immune evasion and reduce tumor growth, is a new potential treatment strategy for PD‐L1‐mediated immune evasion in lung cancer cells." (PMID 35975458, 2022). "Moreover, the FOXM1 pathway is involved in TKI resistance in lung cancer." (PMID 35887129, 2022). "Moreover, FOXM1 could also promote the metastasis of lung cancer cells through the activation of the AKT/p70S6K signal pathway." (PMID 36292640, 2022). "Additionally, overexpression of FOXM1 in lung cancer cells increased PD‐L1 expression in FOXM1‐depleted cells, further supporting the hypothesis that FOXM1 is a positive regulator of PD‐L1 expression." (PMID 35975458, 2022). "In addition, FoxM1 as a tumor marker for lung cancer has been commonly recognized." (PMID 36339610, 2022). "Besides, we verified the function of FOXM1 in a lung cancer cell line." (PMID 36435510, 2022). "Thus, co-activators/co-repressors and epigenetic changes in macrophages could explain distinct functions of FOXM1 during lung cancer, acute injury and lung fibrosis." (PMID 32271749, 2020). "Mechanically, the dysregulation of FOXM1 consequently culminates in abnormalities in the cancer cell proliferation, replication, invasion, metastasis and apoptosis programs, which together contribute to the development of lung cancer and mediate drug resistance." (PMID 30992007, 2019). "Therefore, overexpression of FOXM1 and APOE due to increased level of ROS and OS may induce the risk of lung cancer in these patients." (PMID 29552057, 2017). "We also tested whether FOXM1 induced mucinous adenocarcinomas in a KrasG12D model of lung cancer." (PMID 29267283, 2017). "Thus, to find out whether FoxM1 mediates prognosis in lung cancer through promoting metastasis, we applied lenti-virus transduction to knock down the FoxM1 expression on the migratory and invasive ability of H1299 and PC-9 cells." (PMID 23536876, 2013). "Therefore, our observation makes FoxM1 an attractive target of lung cancer therapy, and could be used as a biomarker for predicting prognosis." (PMID 23536876, 2013). "In human lung cancer samples, increased vimentin and slug expression and decreased E-cadherin expression were found in the groups with high FoxM1 expression, while decreased vimentin and Slug expression and increased E-cadherin expression in the groups with low FoxM1 expression." (PMID 23536876, 2013).
lung cancer (continued). "Since lung cancer lesions contain a heterogeneous population of cells, that includes tumor cells, originated from genetically modified epithelial cells, and different inflammatory and stromal cells, it is important to know the cell autonomous role of Foxm1 during lung tumorigenesis." (PMID 19672312, 2009). "The regulatory function of SOX4, FOXM1, and ETV4, over other key TFs and common DEGs, was highlighted in lung cancer, establishing key co-regulatory complexes in NSCLC and SCLC." (PMID 39228892, 2024). "Consistent with the database results, FOXM1 was downregulated upon FBXO22 silencing and promoted Rad51 expression at the transcriptional and translational levels in lung cancer cells." (PMID 38296976, 2024). "All possible comparisons between co-expression networks of lung cancer and PAH have CCPs, which can be regulated by two top deregulated TFs, FOXM1 and MYBL2, according to the iRegulon analysis." (PMID 36661515, 2023). "Using previously published microarray data of lung cancer (GSE 114761), FoxM1 and PLK1 were upregulated in TGF-β-induced EMT in A549, NCI-H522, NCI-H1944, and NCI-H2122 cells." (PMID 37968723, 2023). "The importance of FOXM1 and MYBL2 in regulating the biological processes that trigger lung cancer can be seen from the smallest CCP formed when comparing all co-expression networks, to the largest CCP formed among RNA-Seq studies of lung cancer." (PMID 36661515, 2023). "Some researchers have revealed that propofol restrained cell malignant phenotypes via downregulating FOXM1 through regulating the circ_RHOT1/miR-326 axis in NSCLC and the circ_TADA2A/miR-155-3p axis or circ_ERBB2/miR-7-5p axis in lung cancer." (PMID 36760719, 2023). "The CCPs formed between lung cancer and PAH have FOXM1 and FOXF1 co-expressed with the most frequent DEGs in microarrays and RNA-Seq datasets, respectively." (PMID 36661515, 2023). "The seven top deregulated transcription factors (SOX4, SOX17, BZW2, FOXM1, ZBTB16, TAL1, and KLF4) consistently appear to be co-expressed with other frequent DEGs and transcription factors throughout the analysis in lung cancer and PAH." (PMID 36661515, 2023). "LINC01426 contributes to clear cell renal cell carcinoma progression by modulating CTBP1/miR-423-5p/FOXM1 axis via interacting with IGF2BP1, and to lung cancer progression via AZGP1 and predicts poor prognosis in patients with LUAD." (PMID 35818395, 2022). "FOXM1 and CENPF expression is positively correlated with lncRNA SBF2-AS1 expression, and their synergistic interaction promotes the proliferation of lung cancer cells." (PMID 35410446, 2022). "Ectopic expression of SCARA5 suppressed proliferation of lung cancer both in vitro and in vivo through upregulation of HSPA5 expression, which inhibited FOXM1 expression resulting in G2/M arrest of the A549 cell line." (PMID 34150631, 2021). "As for the clinical relevance of FAM188B expression in lung cancer, expressions of both FAM188B and FOXM1 are elevated in the human lung cancer tissues." (PMID 33142744, 2020). "The overexpression of forkhead box M1 (FOXM1) promotes MCPH13 expression and proliferation in lung cancer cells." (PMID 32121580, 2020). "A series of studies corroborate that overexpression of FOXM1 and PTIX1 can promote the proliferation of lung cancer cells." (PMID 32294625, 2020). "Here, we demonstrate the oncogenic function of FAM188B via regulation of forkhead box M1 (FOXM1), another oncogenic transcription factor, in lung cancer cells." (PMID 33142744, 2020). "In another type of lung cancer LUSC, NNT-AS1 is a sponge of miR-22, and forkhead box M1 (FOXM1) is the direct target of miR-22." (PMID 33113895, 2020). "FOXM1 and key proteins of the Wnt/β-catenin pathway were upregulated in CD133 + CD44+ lung cancer stem cells (LCSCs) compared with that in CD133 + CD44- cells." (PMID 30992007, 2019). "In lung cancer cells, CDK4/6 inhibition results in suppression of IAPs, FOXM1 and survivin and an augmentation of SMAC and caspase 3 expression." (PMID 30349650, 2018).
lung cancer (continued). "To prove a clinical relevance of FOXM1 in SCLC progression we analyzed FOXM1 expression in 123 patient-derived SCLC samples performing immunohistochemical staining and compared it to other lung cancer entities." (PMID 29228593, 2017). "Analysis of these shortest path genes indicates that some of these genes, such as ESR1, FDXR, ABCA1, IRS1, HSP90AA1, FOXM1, and IGBP1 are related to lung cancer." (PMID 23762832, 2013). "However, lung cancer lesions contain a heterogeneous population of cells, that includes epithelial, inflammatory (macrophages, granulocytes) and stromal cells, that express increased levels of Foxm1 and may influence tumorigenesis." (PMID 19672312, 2009). "Later studies demonstrated that FOXM1 overexpression leads to resistance to gefitinib, an EGFR small molecule inhibitor used as first-line therapy to treat NSCLC in lung cancer cell lines and primary human lung cancer cells." (PMID 39594778, 2024). "In lung cancer, SOX4 expression is probably related to the overregulation of WNT5A; then, SOX4, FOXM1, TCF3, and JUP might form a stable protein complex with other factors and co-factors for the regulation of transcriptional targets." (PMID 39228892, 2024). "Two of the most frequently dysregulated transcription factors are co-expressed in lung cancer and PAH (FOXM1 and FOXF1), while the other six frequently deregulated transcription factors are co-expressed only in lung cancer (TCF21, SOX17, TAL1, LMO2, KLF2, and TBX4)." (PMID 36661515, 2023). "The second suggests a cooperative function between RUNX2 and three transcription factors (BRCA1, FOXM1, and RUNX1) important for the specific regulation of lung cancer establishment and progression, along with three transcription factors (E2F3, FHL2, and TWIST1) of the NSCLC-GRN." (PMID 36551878, 2022). "Overall, SH3PXD2A-AS1 can promote the expression of target genes such as FOXM1, CENPF and KIF20A by binding to the DHX9 protein, thereby promoting the cell cycle progression and cell proliferation of NSCLC, and promoting the growth of lung cancer." (PMID 35410446, 2022). "FOXM1, a member of the Forkhead box (FOX) family of transcription factors, was reported to be transcriptionally regulated by HIF1α under hypoxic conditions and overexpressed in many types of cancers including liver cancer, breast cancer, and lung cancer." (PMID 35365182, 2022). "The small coregulatory network has two winning TFs (FOXM1 and MYBL2) coexpressed in the gene networks that coexpressed with the common winning DEGs between the three types of cancer and the winning DEGs related to lung cancer." (PMID 36101460, 2022). "Furthermore, protein levels of FAM188B and FOXM1 were elevated in the human lung cancer tissues, and FAM188B expression was negatively correlated with the overall survival of lung cancer patients." (PMID 33142744, 2020). "FOXM1 directly activated the AGR2 gene, a key regulator of mucinous phenotype in lung cancer cells." (PMID 29267283, 2017). "Also, our univariate survival analysis showed that low expression of FOXM1 had a significant survival advantage over individuals with tumors expressing high levels of FOXM1 in GBM, breast and Lung cancer patients." (PMID 27764801, 2016). "Because FoxM1 is often elevated in NSCLC, further investigation to see if TZDs can also reduce FoxM1 expression in lung cancer may be worthwhile." (PMID 22778711, 2012). "According to the TRN analysis, SOX4 can be regulated by HOXC6, whereas DLX5 can be regulated by SOX4, FOXM1, and ETV4, and according to the co-regulatory network analysis, they both participate in the formation of TF complexes in both subtypes of lung cancer (NSCLC and SCLC)." (PMID 39228892, 2024). "According to the TRN of lung cancer, SOX4, FOXM1, ETV4, HOXC6, and E2F3 are the main positive regulators, whereas SOX17, KLF4, and ZBTB16 are the main negative regulators of transcription, controlling the expression of other TFs and target genes in lung cancer." (PMID 39228892, 2024).
lung cancer (continued). "Moreover, FOXF1 is also co-expressed in the CCP of the LC RNA-Seq datasets, along with seven of the most frequently dysregulated TFs (FOXM1, SOX17, TAL1, TCF21, TBX4, LMO2, and KLF2), suggesting its importance as a regulator of gene expression during lung cancer progression." (PMID 36661515, 2023). "Moreover, FOXM1 is co-expressed in the CCPs of LC microarray datasets, and PAH, FOXM1, and MYBL2 are co-expressed in the CCP of all LC microarray datasets, suggesting their key importance during the lung cancer oncogenic process." (PMID 36661515, 2023). "As expected, IHC staining revealed that protein expressions of FOXM1, HJURP, and PTTG1 were all significantly elevated in tumors compared with adjacent normal tissues, indicating that SRS genes may play an important in lung cancer progression." (PMID 34869385, 2021). "The crude hazard ratio (HR) of FoxM1 strong expression compared with FoxM1 negative or weak expression was 1.899 (95% CI, 1.016–3.551, P<0.05), which indicated that strong FoxM1 status increased the hazard of lung cancer related death by nearly two times that of negative or weak FoxM1 status." (PMID 23536876, 2013). "Moreover, our findings may lead to new biomarkers as well as therapies that might target distinct LUAD subgroups associated with poor survival; small molecule inhibitors for MYB family members as well as FOXM1 have been developed but have not yet been tested in lung cancer." (PMID 32925947, 2020).